AQP4 (aquaporin 4)
Diseases named in the same sentence as AQP4 in open-access papers (continued):
Sharing a sentence is not in itself a finding about the gene and the disease.
neuromyelitis optica spectrum disorder (continued). "Moreover, the safety of SARS-CoV2 vaccines has been highlighted in adult MS and in adult patients with aquaporin-4-IgG neuromyelitis optica spectrum disorder (AQP4-IgG+NMOSD) and myelin oligodendrocyte glycoprotein associated disease (MOGAD)." (PMID 36761740, 2023). "However, incontrast to aquaporin 4-IgG-seropositive neuromyelitis optica spectrum disorder,visual recovery tends to be more favorable, with good response to steroidtreatment." (PMID 35170658, 2023). "Therefore, we aimed to investigate the prevalence of PHOMS in patients with (i) aquaporine-4-IgG-positive (AQP4) neuromyelitis optica spectrum disorders (AQP4 + NMOSD) and (ii) myelin oligodendrocyte glycoprotein-IgG (MOG)-associated disease (MOGAD)." (PMID 36245037, 2023). "Clinically, there are distinct clinical and radiological features which distinguish MOGAD from multiple sclerosis and from aquaporin-4-seropositive neuromyelitis optica spectrum disorder (AQP4 + NMOSD) that have led to MOGAD being treated as a distinct disease." (PMID 37845760, 2023). "Furthermore, an adenosine triphosphate-binding cassette transporter of Clostridium perfringens shared sequence homology with Aquaporin-4 (AQP4), of which autoantibodies are pathogenic for neuromyelitis optica spectrum disorders (NMOSD)." (PMID 35844606, 2022). "AQP4 contributes to the development of inflammatory demyelination diseases of the CNS (neuromyelitis optica spectrum disorder [NMOSD] or acute disseminated encephalomyelitis [ADEM]) and promotes brain inflammation in neurodegenerative diseases, stroke, and other disorders." (PMID 35386692, 2022). "This review focused primarily on AQP4, gliogenesis, and hydrocephalus, other pathologies associated with AQP4 such as neuromyelitis optica or gliomas were not covered." (PMID 36142348, 2022). "Over the last decade, several studies have helped delineate the characteristic clinical-MRI phenotypes of the disease, allowing distinction from aquaporin-4 (AQP4)-IgG-positive neuromyelitis optica spectrum disorder (AQP4-IgG+NMOSD) and multiple sclerosis (MS)." (PMID 35785363, 2022). "Neuromyelitis optica spectrum disorder (NMOSD) is an inflammatory demyelinating autoimmune disease of the central nervous system (CNS) featured with a specific autoantibody directed against AQP4 in most of patients." (PMID 36248814, 2022). "Satralizumab, Denosumab, and Brodalumab (Siliq) are monoclonal antibodies FDA-approved to treat anti-aquaporin-4 (AQP4) antibody-positive neuromyelitis optica spectrum disorder (NMOSD), postmenopausal osteoporosis, and moderate to severe plaque psoriasis in adult patients, respectively." (PMID 35628390, 2022). "These are pathogenic mechanisms that depend on the antibody Fc region of IgG1-3 subclass antibodies, such as acetylcholine receptor (AChR) antibodies in myasthenia gravis, NMDAR antibodies in autoimmune encephalitis or of antibodies against aquaporin 4 (AQP4) in neuromyelitis optica." (PMID 35401530, 2022). "AQP4 controls bidirectional fluid exchange and has been linked to several pathological processes including paediatric brain neoplasms with dysfunctional BBB and the neuroimmunological disorder neuromyelitis optica." (PMID 36499600, 2022). "An example that complement activation can lead to bystander-induced neuronal injury was recently described in aquaporin-4-positive neuromyelitis optica suggesting that a complement-bystander injury may be a general mechanism for early neuronal injury." (PMID 36712429, 2022). "The discovery of anti-aquaporin-4 (AQP4) antibody (Ab) was essential for the evolution of NMO diagnostic criteria, leading to its reclassification as a member of a larger group of disorders called neuromyelitis optica spectrum disorders (NMOSD)." (PMID 35614913, 2022). "For example, neuromyelitis optica (NMO) is an autoimmune disease targeting AQP4." (PMID 35439261, 2022).
neuromyelitis optica spectrum disorder (continued). "Neuromyelitis optica (NMO) is an autoimmune demyelinating disease of the central nervous system characterized by the presence of autoantibodies (called NMO-IgG) targeting aquaporin-4." (PMID 36751497, 2022). "Notably, in family B the mother had SLE from her mid-twenties and the daughter was diagnosed with neuromyelitis optica in the presence of ANAs and antibodies to aquaporin-4 (AQP4-Ab, also known as NMO-IgG) in the serum and cerebrospinal fluid." (PMID 35477763, 2022). "Additionally, neuromyelitis optica spectrum disorder, characterized by central nervous system inflammation and demyelination, is mediated by anti-aquaporin-4 (anti-AQP4) auto-antibodies targeting astrocytes and subsequent complement activation." (PMID 36275687, 2022). "Inflammatory myelopathies can be recognized in the context of numerous immune-mediated disorders, including multiple sclerosis (MS), aquaporin-4(AQP4)-IgG-positive neuromyelitis optica spectrum disorders (AQP4+NMOSD), and myelin oligodendrocyte glycoprotein (MOG) antibody-associated disease (MOGAD)." (PMID 36330423, 2022). "The most common Antibody (Ab)-mediated disorders of the central nervous system (CNS) are aquaporin-4 antibody neuromyelitis optica spectrum disorders (AQP4+NMOSD), myelin-oligodendrocyte glycoprotein antibody-associated disease (MOGAD), and autoimmune encephalitis (AE)." (PMID 36601293, 2022). "Neuromyelitis optica spectrum disorder (NMOSD) is an inflammatory disease of the central nervous system characterized by relapses and autoimmunity caused by antibodies against the astrocyte water channel protein aquaporin-4." (PMID 35887254, 2022). "Multiple sclerosis (MS), aquaporin-4-antibody-positive neuromyelitis optica spectrum disorder (AQP4-Ab-positive NMOSD), and myelin oligodendrocyte glycoprotein antibody-associated disease (MOGAD) are distinct inflammatory demyelinating disorders of the central nervous system." (PMID 35837405, 2022). "Autoantibodies targeting the aquaporin-4 (AQP4) channel, which is enriched on the surface of astrocytes and is involved in maintaining the stability of the blood–brain barrier (BBB), for example, cause neuromyelitis optica spectrum disorders (NMODSs)." (PMID 36385950, 2022). "Autoantibodies directed to AQP4 are at the basis of the pathogenesis of neuromyelitis optica (NMO), an inflammatory CNS disorder characterized by astrocyte loss, axonal damage and demyelination, while the occurrence of anti-Kir 4.1 antibodies in MS is controversial." (PMID 35707531, 2022). "The latest criterion of diagnostic guidelines unifies AQP4-negative and positive forms under the umbrella of neuromyelitis optica spectrum disorders (NMOSDs)." (PMID 34445668, 2021). "Ravulizumab, a newer humanized mAb against C5 with less frequent infusion regimen compared to eculizumab is being evaluated for efficacy and safety in a Phase 3, placebo-controlled, open-label, multicenter study in adult patients with anti-AQP-4 (+) neuromyelitis optica spectrum disorder (NMOSD)." (PMID 33530460, 2021). "However, there is mounting evidence for an immune-mediated mechanism, as there are several case reports of aquaporin-4 antibody (AQP4-IgG) positive neuromyelitis optica spectrum disorder (NMOSD) following VZV infection." (PMID 34737756, 2021). "Neuromyelitis optica spectrum disorder (NMOSD) is a type of astrocytopathy in which aquaporine-4 (AQP4)-IgG antibodies bind to AQP4 water channels on the end feet of astrocytes, leading to immune-mediated inflammation and secondary demyelination that can occur in varying degrees." (PMID 34526962, 2021). "Based on clinical, radiological and immunologic features, this condition, now called ‘MOG-immunoglobulin G (IgG)-associated encephalomyelitis’, is considered a separate disease entity, distinct from AQP4-positive neuromyelitis optica as well as from multiple sclerosis." (PMID 33419217, 2021).
neuromyelitis optica spectrum disorder (continued). "Neuromyelitis optica spectrum disorder (NMOSD) is an autoimmune inflammatory disease of the central nervous system (CNS), characterized by pathogenic, complement-activating autoantibodies against the main water channel in the CNS, aquaporin 4 (AQP4)." (PMID 33986750, 2021). "Eculizumab safety is substantiated in numerous studies as well as almost two decades of case studies for its four other FDA indications (AchR + generalized myasthenia gravis, atypical hemolytic uremic syndrome, paroxysmal nocturnal hemoglobinuria, and anti-AQP4 neuromyelitis optica)." (PMID 34960699, 2021). "In multiple sclerosis, magnetic resonance imaging (MRI) new silent lesions contribute to the diagnostic criteria, have prognostic value, and are used in treatment monitoring; but in aquaporin-4 antibody neuromyelitis optica spectrum disorder (AQP4-NMOSD), they are rare between attacks." (PMID 34878547, 2021). "Children who present with neuromyelitis optica with negative AQP4-Abs should be evaluated for biotinidase deficiency." (PMID 35265569, 2021). "This cohort study assesses the frequency and characteristics of new brain and spinal cord silent lesions on magnetic resonance imaging in seropositive patients with myelin oligodendrocyte glycoprotein antibody disease or aquaporin-4 antibody neuromyelitis optica spectrum disorder." (PMID 34878547, 2021). "A dual diagnosis of sarcoidosis and neuromyelitis optica with aquaporin-4 antibodies is very rare." (PMID 34166585, 2021). "The main differential diagnoses are neuromyelitis optica spectrum disorders, in which anti-AQP-4 antibodies are usually present and brain magnetic resonance imaging may show abnormal signals." (PMID 31977873, 2020). "Based on clinical, immunological and histopathological evidence, MOG-IgG-associated encephalomyelitis (MOG-EM) has emerged as a distinct disease entity different from multiple sclerosis (MS) and aquaporin-4-antibody-positive neuromyelitis optica spectrum disorder (NMOSD)." (PMID 32055995, 2020). "It involves multiple autoantigens (contrary for example to neuromyelitis optica that involves reactivity to Aquaporin-4, AQP4) that can vary between patients depending on genetic characteristics, age, environmental and/or triggering factors, and duration of the disease." (PMID 32486045, 2020). "In the past few years, growing clinical, immunological and histopathological evidence suggests that MOG-EM can now be considered as a clearly distinct disease entity from both multiple sclerosis (MS) and aquaporin-4-positive neuromyelitis optica spectrum disorder (NMOSD)." (PMID 32055995, 2020). "The proof-of-concept of such new therapeutic approach is currently being evaluated using non-pathogenic anti-AQP4 antibodies (aquaporumab) for the treatment of neuromyelitis optica characterized by the presence of autoantibodies against AQP4." (PMID 32630469, 2020). "MOG antibody-associated disease has similarity to Neuromyelitis Optica Spectrum Disorders (NMOSD) in terms of clinical and imaging phenotypes, suggesting that patients within the aquaporin 4 (AQP4) antibody seronegative cohort become suspects for MOG antibody-associated disease." (PMID 33510701, 2020). "Furthermore, monoclonal antibodies such as anti-AQP4 have been shown to be promising agents in the treatment of neuromyelitis optica (NMO) and clinical trials are in progress to evaluate the efficacy of anti-AQP4 IgG in NMO and multiple sclerosis." (PMID 32765303, 2020). "EAAT2 and AQP4 both existed in the astrocytic end-foot membrane as macro-molecular complexes, and both are also depleted from plasma membranes of cultured astrocytes, exposed to neuromyelitis optica immunoglobulin G (NMO-IgG)." (PMID 32012713, 2020).
neuromyelitis optica spectrum disorder (continued). "A 25 year-old Nigerian woman with aquaporin-4 antibody-positive neuromyelitis optica spectrum disorder (NMOSD) presented with a 6 week history of nausea, vomiting, and refractory hiccups; as well as progressive lower extremity sensory loss, weakness, saddle anesthesia, and urinary incontinence." (PMID 32477258, 2020). "Aquaporin 4 (AQP4)-specific antibodies (AQP4-abs) are found in the majority of patients with neuromyelitis optica spectrum disorder (NMOSD), a severe autoimmune disease of the central nervous system (CNS) culminating in antibody-mediated destruction of astrocytes." (PMID 30564980, 2019). "Clinical trials for neuromyelitis optica treatments using anti-AQP4 IgG are in progress." (PMID 30934923, 2019). "However, dimethyl fumarate for MOG antibody disease was not harmful compared with when disease-modifying drugs (DMDs) of MS were used for anti-aquaporin-4 antibody-positive neuromyelitis optica." (PMID 31824807, 2019). "Previous publications showed a presence of anti-AQP4 antibodies during the inflammatory and demyelinating phase of neuromyelitis optica, which indicated that this molecule might represent a specific target in demyelinating diseases of the CNS." (PMID 31409036, 2019). "Intravenous immunoglobulin may be a rescue therapy in aquaporin-4-IgG-positive neuromyelitis optica attacks in pregnant women, especially those with severe infections." (PMID 29552355, 2018). "Anti-AQP4-antibodies were the first antibodies with a clearly defined target that were identified in patients with demyelinating diseases and now serve as biomarker for the diagnosis of patients with neuromyelitis optica spectrum disorders (NMOSD)." (PMID 30364136, 2018). "A variety of neurological complications of Dengue virus infection such as dengue fever (DF) with the phenotype of neuromyelitis optica spectrum disorder (NMOSD) presented with brainstem symptoms or isolated unilateral optic neuritis tested positive for serum AQP4 antibody." (PMID 30555637, 2018). "Most experts now consider MOG-IgG-associated encephalomyelitis (MOG-EM) a disease entity in its own right, immunopathogenetically distinct from both classic multiple sclerosis (MS) and aquaporin-4 (AQP4)-IgG-positive neuromyelitis optica spectrum disorders (NMOSD)." (PMID 29724224, 2018). "Neuromyelitis optica spectrum disorders (NMOSD) are demyelinating autoimmune diseases in the central nervous system (CNS) that are characterized by the presence of anti-aquaporin four antibodies (AQP4-IgG) in the serum." (PMID 28679367, 2017). "(iii) The retina might be a primary target of AQP4‐specific T cells and neuromyelitis optica immunoglobulin G: AQP4‐specific T cells alone are sufficient to cause retinitis with low‐grade axonal pathology in the retinal nerve fiber/ganglionic cell layer." (PMID 28344667, 2017). "Clinical manifestations are diverse and may include symptoms typically seen in AQP4-IgG-positive neuromyelitis optica, such as INV and respiratory insufficiency, or in multiple sclerosis, such as INO." (PMID 27802825, 2016). "Animal transfer experiments could validate human anti-D2R antibody pathogenicity, as demonstrated for anti-AQP4 antibody in neuromyelitis optica and anti-NMDAR antibody in encephalitis." (PMID 27908295, 2016). "Although no known muscle disease is associated with AQP4, AQP4-antibody induces astrocytic necrosis in neuromyelitis optica (NMO), which has been classified as a subtype of multiple sclerosis (MS)." (PMID 26230713, 2015). "Neuromyelitis optica and neuromyelitis optica spectrum disorder (NMO/NMOSD) is a rare but clinically aggressive demyelinating disease of the central nervous system (CNS) caused by antibodies against water channel protein aquaporin 4 (AQP4) in the astrocytic foot processes." (PMID 26433388, 2015).
neuromyelitis optica spectrum disorder (continued). "A recent case report of alemtuzumab therapy in an AQP4-antibody positive NMO (neuromyelitis optica) patient demonstrated a progressive and lethal disease course with massive CNS monocytic infiltration further substantiating insufficient suppression of the innate immune system by alemtuzumab." (PMID 26204829, 2015). "Thus, antibodies against AQP4 are detectable in the cerebrospinal fluid (CSF) of most patients with neuromyelitis optica (NMO) spectrum disease, mainly when it is worsening." (PMID 27379319, 2014). "Neuromyelitis optica (NMO) is an inflammatory demyelinating disease of the central nervous system (CNS), which is characterized by the presence of pathogenic serum autoantibodies against aquaporin 4 (AQP4) in the vast majority of patients." (PMID 24367907, 2013). "Intravenous and oral corticosteroid therapies are commonly used to treat anti-aquaporin 4 antibody-positive neuromyelitis optica (NMO), and plasmapheresis is also beneficial for patients with acute, severe vision loss who have optic neuritis that is refractory to corticosteroid therapy." (PMID 23575376, 2013). "In this study we analysed the clinical and paraclincal features associated with myelitis and optic neuritis in a large cohort of Caucasian patients with neuromyelitis optica spectrum disorders in a stratified fashion according to the patients' AQP4-Ab serostatus." (PMID 22260418, 2012). "Because neuromyelitis optica seems to have a more aggressive course than general MS and seems to respond better to classical immunosuppression than to immunomodulation, detection of AQP4 antibodies helps to classify patients and aids in treatment decisions." (PMID 23035757, 2012). "The current concept of neuromyelitis optica is based on the idea that this disease might be an astrocyte disease with astrocytic AQP4 as a major molecular target of the adaptive immune response." (PMID 21264240, 2011). "Similar to neuromyelitis optica (NMO) where specific autoantibodies kill aquaporin-4 expressing astrocytes, a cytotoxic attack of myelin presenting astrocytes could contribute to the pathology in optic nerve and spinal cord of EAE and MS lesions." (PMID 21209700, 2010). "Clinical and neuroradiological characteristics of 23 patients with neuromyelitis optica or relapsing myelitis who are seropositive for AQP4 autoantibodies by cell-based IIFA, divided into those who are seropositive and seronegative for NMO-IgG by tissue-based IIFA." (PMID 20822515, 2010). "Similarly, in antibody-mediated optic neuritis (e.g., myelin oligodendrocytic glycoprotein (MOG) or aquaporin-4 (AQP4) neuromyelitis optica spectrum disorder), inflammatory cytokines precipitate cellular congestion, hampering molecular traffic across the optic nerve head." (PMID 40001676, 2025). "Previous reports of patients with myelitis associated with rheumatologic disease may have had unrecognized aquaporin-4 (AQP4)-IgG seropositive neuromyelitis optica spectrum disorder (NMOSD) or myelin oligodendrocyte glycoprotein (MOG)-IgG–associated disease (MOGAD)." (PMID 39442039, 2025). "Proof of concept for this hypothesis has been provided, for example, by antibodies against glucose-regulated protein 78 (GRP78) in addition to aquaporin 4 (AQP4) in patients with neuromyelitis optica spectrum disorder (NMOSD) or antibodies against unconventional Myosin-X in NMDAR encephalitis." (PMID 39142424, 2024). "However, it can also be the first clinical presentation of other acquired demyelinating syndromes (ADS), including multiple sclerosis (MS), aquaporin-4-IgG positive neuromyelitis optica spectrum disorder (NMOSD) or myelin oligodendrocyte glycoprotein antibody-associated disease (MOGAD) diagnosis." (PMID 38915059, 2024). "The term neuromyelitis optica spectrum disorder (NMOSD) includes conditions with an autoimmune genesis that are manifested by attacks of optic neuritis (ON) and transverse myelitis (TM) and also express aquaporin 4 (NMO-IgG) antibodies." (PMID 39781148, 2024).